IL1B (interleukin 1 beta)
Diseases named in the same sentence as IL1B in open-access papers (continued):
Sharing a sentence is not in itself a finding about the gene and the disease.
Hypertension (207 papers, 2008 to 2026). The presence of chronic increased pressure in the systemic arterial system. "Hypertension is strongly associated with increased circulating levels of proinflammatory cytokines such as IL‐1β, IL‐6, and TNF‐α." (PMID 40454610, 2025). "A previous study demonstrated that MCC950 (10 mg/kg) can successfully reduce myocardial fibrosis and IL-1β levels when given three times to patients with hypertension caused by angiotensin II infusion." (PMID 40079000, 2025). "No previous studies have reported an association between salivary IL-1β and the diagnosis of hypertension." (PMID 40572711, 2025). "IL-1β and IL-18 concentrations are elevated in the circulation of patients with essential hypertension, and this increase is associated with elevated blood pressure." (PMID 40572711, 2025). "Recent studies also suggest that HPD intake can cause intraglomerular hypertension and increase the risk of chronic kidney disease, which in turn is associated with a higher risk of AF as a result of elevated circulating IL-1β levels." (PMID 38247800, 2024). "Second, reducing SCFAs leads to an increase in proinflammatory cytokines, including TGF-β1, TNF-α, IL-1β, and IL-6, which in turn causes a reduction in glomerular filtration rate and consequently results in hypertension." (PMID 37273529, 2023). "Both IL-1β and IL-23 amplify the production of IL-17A, which is responsible for causing end-organ damage and hypertension." (PMID 37266014, 2023). "IL-1β plasma level was positively associated with hypertension, whereas the circulating level of IL-6 was positively correlated with the age in CABG cohort." (PMID 37745103, 2023). "Apigenin improves hypertension and cardiac hypertrophy in spontaneously hypertensive rats, which are associated with the downregulation of inflammatory factors, such as IL-1β, IL-6, and iNOS in the hypothalamic paraventricular nucleus." (PMID 35955548, 2022). "IL-1β and IL-18 are associated with hypertension and hypertensive patients exhibit enhanced levels of IL-1β." (PMID 33494430, 2021). "Although it is accepted that IL-1β is highly associated with the development of hypertension, its effects and underlying regulatory mechanisms are far from fully understood, and some reports are still controversial." (PMID 34445357, 2021). "We also discuss the new progress in understanding how ncRNAs control the activity of IL-1β and its associated proteins in the context of hypertension." (PMID 34445357, 2021). "Based on the high relevance and association of IL-1β to hypertension, recent studies have led to the discovery of several ncRNAs that target this gene." (PMID 34445357, 2021). "Over recent years IL-1β has been linked in various types of hypertension such as SAH, PH, and GH, highlighting the importance of this interleukin in the progression of hypertension." (PMID 34445357, 2021). "For example, tumour necrosis factor‐α (TNF‐α), interleukin‐6 (IL‐6) and interleukin‐1β (IL‐1β) cause chronic low‐grade inflammation in hypertension." (PMID 34331512, 2021). "Noncoding mutations in NLRP3 were reported to be linked to hypertension susceptibility, and the expression of IL-1β was elevated in patients with essential hypertension." (PMID 31694192, 2019). "Since calcification is closely linked with hypertension, aging and cardiovascular mortality, it would be particularly interesting to investigate caspase-1 activation and IL-1β release from VSMCs derived from hypertensive patients." (PMID 29274344, 2018). "Apart from its inflammatory role, IL-1β is a pyrogenic cytokine that in small concentrations induces the production of other cytokines such as IL-6 and can cause hypertension and fever." (PMID 19696895, 2009). "Increased renal expression of IL-6 and IL-1b is associated with hypertension." (PMID 41184958, 2025). "Furthermore, IL-1β produced by the myeloid cells is also associated with exacerbation of hypertension." (PMID 37266014, 2023).
Hypertension (continued). "A growing amount of evidence has confirmed the association between IL-1β and hypertension." (PMID 36703963, 2022). "Several genes are associated with vascular disease and hypertension during pregnancy via impaired inflammatory response, hypoxia, and oxidative stress, such as cytokines/chemokines IL-1β, IL-6, IL-8, and impairment expression in endothelial cells/VSMCs of HIF1α and eNOS genes." (PMID 34867473, 2021). "In addition, we reviewed recent studies that highlight novel findings examining the function of non-coding RNAs in regulating the activity of IL-1β and its associated proteins in the setting of hypertension." (PMID 34445357, 2021). "Similarly the inflammasome was shown to be involved in cardiac arrhythmias, and higher levels of IL-1β and IL-18 have been associated with hypertension." (PMID 33149733, 2020). "The presence of IL-1β is strongly associated with cardiovascular diseases, which could cause a long-term derangement of the heart and autonomic function; while its inhibition decreases AP, arterial hypertension and residual inflammatory risk." (PMID 34635094, 2021). "The downregulation of IL-10 and upregulation of TNF-α and IL-1β show a sustained inflammatory state, which is consistent with hypertension-driven low-grade inflammation as well as increased production of trimethylamine N-oxide (TMAO) in hypertensive models." (PMID 41515269, 2026). "This study demonstrates that fecal microbiota transplantation from PE rats induces preeclampsia-like symptoms, including hypertension, renal impairment, and systemic inflammation characterized by elevated IL-1β, IL-8, and TNF-α." (PMID 41459234, 2025). "Inflammatory factors secreted by PRAT, such as TNF-α and IL-1β, also play a significant role in the pathogenesis of hypertension." (PMID 40487756, 2025). "In our study, the pro-inflammatory marker IL-1β in saliva was found at higher concentrations in relation to the diagnosis of hypertension." (PMID 40572711, 2025). "IL-1β and IL-18, the inflammasome-induced cytokines play critical roles in hypertension and inhibition of IL-1β has shown potential in reducing blood pressure and preventing the development of hypertension." (PMID 40433411, 2025). "Significant correlations were found between serum NLRP3 levels and the presence of hypertension (p = 0.001) and between saliva IL-1β levels and the presence of hypertension (p = 0.010)." (PMID 40572711, 2025). "This hypertension model is associated with inflammation in the kidney, and the NLRP3/IL1β/IL-18 signaling system is involved." (PMID 39576390, 2025). "Evidence indicates that IL-1β contributes to the development of hypertension through its inflammation-mediating signaling and by regulating the function of vascular smooth muscle cells and remodeling the extracellular matrix." (PMID 40572711, 2025). "Evidence suggests that IL-1β and IL-18 levels in blood and vascular tissues are elevated in hypertension." (PMID 40572711, 2025). "This cascade triggers the release of pro-inflammatory cytokines, including TNF-α, IL-1β, and IL-17, which collectively promote vascular dysfunction, renal sodium retention, and sympathetic overactivity—all key mechanisms driving hypertension." (PMID 41322424, 2025). "Among these, IL-1β and IL-18 are consistently elevated in essential hypertension and act as key mediators of vascular inflammation and end-organ damage." (PMID 40832143, 2025). "Several studies have found that patients with essential hypertension have high serum IL-1β levels, suggesting the pro-hypertensive effects of IL-1β." (PMID 40572711, 2025). "NLRP1 and itsdownstream molecules ASC (adaptive signal transduction molecules) can activatepro-inflammatory factors IL-1β and IL-18 through a caspase-1-dependentpathway, thereby aggravating vascular inflammation and leading to the occurrenceof hypertension." (PMID 39077331, 2024).
Hypertension (continued). "Immune cells in the brain, including microglia/macrophages, are impacted by hypertension, leading to their activation and expression of pro-inflammatory molecules like IL-1b, IL-6, and TNF-a." (PMID 39144717, 2024). "Hypertension can induce increased expression of IL-1β through various components of the NLRP3 inflammasome." (PMID 39867890, 2024). "In patients with resistant hypertension and mild hypertension, levels of plasma IL-1β and IL-10 were elevated compared to those with normal blood pressure." (PMID 38791032, 2024). "Individuals with hypertension display elevated levels of pro-inflammatory cytokines, including IL-1β, IL-6, IL-8, IL-17, IL-23, TGF-β, and TNF-α." (PMID 38672199, 2024). "Elevated levels of circulating IL-1β in hypertension lead to prostaglandin E2 overexpression in PVM, which excites neurons in hypothalamic paraventricular nuclei (via EP3 receptor signaling) and increases SNS activity." (PMID 39495252, 2024). "The increased level of pro-inflammatory cytokines such as interleukin-1 beta and tumor necrosis factor-alpha (TNF-α) has made hypertension a low-grade inflammatory disease (IL-1β)." (PMID 39171117, 2024). "The putative mechanism is that IL-1β promotes the occurrence and development of hypertension by altering the responses of endothelial cells, the immune system, and the central nervous system." (PMID 38791032, 2024). "Taken together, these analyses support an enhanced gene regulatory influence of adrenal Agtr1a as well as a diminished gene regulatory influence of Th, Ccl5, Agtr1a, and Il1b from the CVLM in regulating the progression of hypertension in females." (PMID 39514592, 2024). "While the usefulness of IL-1β as a therapeutic target for hypertension remains controversial, IL-18 levels in the blood were associated with higher blood pressure." (PMID 38256155, 2024). "Interleukin 1 beta (IL-1B) is a member of the interleukin 1 cytokine family that increases hypertension and negatively impacts end-organs during high blood pressure." (PMID 36685671, 2023). "The present study demonstrated for the first time that endothelial CD38 activation and subsequently accelerated NAD+ degradation due to enhanced macrophage-derived IL-1β production was responsible for BP elevation and vascular damage in hypertension." (PMID 37718359, 2023). "Increased NLRP3 inflammasome activity is necessary for high salt diet-induced increase in IL-1β expression and for increased blood pressure in an angiotensin II-primed mouse model of hypertension." (PMID 37293263, 2023). "Activated MPS within hypertension leads to ROS production and generation of the cytokines IL-1β and TNFα, which is covered in greater detail in this review referenced here." (PMID 36970367, 2023). "The study found that, compared with the normal population, serum IL-1β levels in patients with essential hypertension increased." (PMID 36873396, 2023). "Compared with normal people, the levels of serum IL-1β and IL-18 are higher in patients with hypertension." (PMID 35668772, 2022). "MALAT1 enhances the levels of proinflammatory cytokines (IL-18 and IL-1β) in pregnancy-induced hypertension by activating the NF-κB pathway." (PMID 35626352, 2022). "Considering the tight association with hypertension and the essential role in inflammation, more and more studies on how the IL-1β involves in pathophysiological mechanisms of hypertension have been performed and explored." (PMID 36703963, 2022). "Prior observation discovered that serum IL-1β level was elevated in patients with high blood pressure." (PMID 36204568, 2022). "High levels of IL-1β have been detected in the serum of patients with essential hypertension in recent studies, indicating the role of IL-1β in elevating blood pressure." (PMID 36703963, 2022). "Specifically, a growing amount of evidence points to a possible link between hypertension and interleukin-1β (IL-1β), a well-characterized mediator of inflammation." (PMID 34445357, 2021).
Hypertension (continued). "We also outlined the new progress in elucidating the potential mechanisms of IL-1β in hypertension, focusing on it’s regulation in inflammation, vascular smooth muscle cell function, and extracellular remodeling." (PMID 34445357, 2021). "There seems to be a strong link between genes favoring an enhanced status of inflammasome activation, IL-1β levels, arterial hypertension, and reduced longevity." (PMID 33443617, 2021). "The collected information highlighted here suggest that IL-1β participates in the development of hypertension through its mediated inflammatory signaling and by regulating VSMC function, and ECM remodeling." (PMID 34445357, 2021). "IL-1β is well recognized as clinically relevant given its high abundance in patients with hypertension." (PMID 34445357, 2021). "The ex vivo study showed that siRNA-based TIFA protein expression silencing in PBMCs obtained from systemic hypertension or PAH patients resulted in a significant reduction of both IL-1β and TNF-α levels." (PMID 34238983, 2021). "Patients with essential hypertension and animal models of hypertension exhibit elevated levels of circulating IL-1β." (PMID 33494430, 2021). "Here we shed some light on recent advances related to IL-1β mediated phenotypic changes in VSMCs occurring during the development of hypertension in both inflammatory dependent and independent mechanisms." (PMID 34445357, 2021). "Mounting evidence suggests that interleukin-1β (IL-1β) plays a significant role in the pathogenesis of various types of hypertension." (PMID 34445357, 2021). "Because of its essential role in inflammation, examination of how IL-1β influences vascular pathology-related changes in hypertension has gained much interest and is currently being explored." (PMID 34445357, 2021). "Most of those genes were involved in the IL-1β pathway, thus implying an overstimulation of the inflammasome pathway in these cells during hypertension." (PMID 33494430, 2021). "Taken together, the effectiveness of ncRNAs targeting IL-1β in preventing hypertension further suggests that this pathway is a likely target." (PMID 34445357, 2021). "Here we summarized the new progress in the study of IL-1β, focusing on three common types of hypertension, e.g., SAH, PH, and GH, in terms of it’s pro-inflammatory effects." (PMID 34445357, 2021). "The levels of pro‐inflammatory factors such as TNF‐α, IL‐1β and IL‐6 increase with the severity of hypertension, and affect its prognosis." (PMID 34331512, 2021). "Its inhibitory actions are characterized by preventing high blood pressure and lowering IL-1β levels." (PMID 34445357, 2021). "For example, a few studies have found that patients with essential hypertension displayed high levels of IL-1β in their serum, indicating the pro-hypertensive effects of IL-1β." (PMID 34445357, 2021). "At the 2-year follow-up, higher systolic and diastolic BP, and IL-1β levels were found in the hypertension group compared to the controls after adjusting for follow-up BMI." (PMID 32292598, 2020). "Although it is known that there are increased levels of circulating IL-1β in hypertension, only recently has the inflammasome activation been suggested to play a role in its production." (PMID 32852643, 2020). "In summary, we showed that AZD8797, a CX3CR1 inhibitor, attenuated fructose-induced hypertension and expression of pro-inflammatory cytokines, IL-1β, IL-6, and TNF-α." (PMID 32532282, 2020). "In the present study, baseline hs-CRP and IL-1β levels in the hypertension group were significantly higher than those in the control group (normal BP at both baseline and follow-up), whereas baseline IL-6 levels showed an increasing trend." (PMID 32292598, 2020). "Hypertensive patients have higher circulating levels of the inflammatory cytokines IL-1β, IL-10, and tumor necrosis factor-alpha (TNF-α), indicating the potential use of these inflammatory biomarkers as markers for hypertension." (PMID 33265898, 2020).
Hypertension (continued). "ICV administration of AZD8797, a CX3CR1 inhibitor, attenuates fructose-induced hypertension and expression of pro-inflammatory cytokines IL-1β, IL-6, and TNF-α." (PMID 32532282, 2020). "Elevated levels of IL-1β, IL-10, and TNF-α are also correlated with increased arterial stiffness associated with hypertension." (PMID 33265898, 2020). "Lastly, we observed that expression of hsa-miR-30a-5p, a negative regulator of microvascular network density and regulator of pro-inflammatory cytokine levels, was correlated with hypertension and with the expression of IL1β." (PMID 33353159, 2020). "And NLRP3 inflammasome was involved with CaSR-mediated fibrosis during hypertension, which led to IL-1β and IL-18 release." (PMID 30906225, 2019). "The NLRP3 inflammasome, a key signaling platform that activates highly proinflammatory cytokines, IL-1β and IL-18, contributes to the development of aortic aneurysms and hypertension via vascular inflammation." (PMID 30906225, 2019). "Several studies agree that hypertensive patients showed increased IL-1β secretion under stimulation with LPS." (PMID 31186952, 2019). "In turn, IL-17 induces IL-1β, IL-6, and TNF-α secretion, also associated with endothelial dysfunction and hypertension." (PMID 31186952, 2019). "Chemokines such as C-C motif chemokine ligand 2 (CCL2), and pro-inflammatory cytokines such as tumor necrosis factor alpha (TNF-α) and interleukin 1 beta (IL-1β), are upregulated both peripherally and centrally in hypertension." (PMID 31427987, 2019). "IL-1β in essential hypertension enhances VCAM-1, ICAM-1, and E-selectin expression with atherosclerotic effects." (PMID 31186952, 2019). "The production of cytokines like IL-6, IL-23, and IL-1β can also skew T cells produce IL-17A, which we have previously shown to be involved in hypertension." (PMID 29800237, 2018). "Increased circulating levels of pro-inflammatory cytokines (PICs) including Tumor necrosis factor alpha (TNF-α), Interleukin-6 (IL-6), and Interleukin-1 beta (IL-1β) have been noted in both human hypertension and animal models of hypertension." (PMID 29520237, 2018). "A recent study of over 100 individuals identified a sub-group of older people with hypertension that had elevated inflammasome gene expression profiles and constitutive IL-1β expression." (PMID 29274344, 2018). "On the other hand, IL-1β has been known to be elevated in individuals with hypertension, which leads to renal and vascular inflammation." (PMID 30429496, 2018). "Reports have demonstrated that various PICs such as TNF-α, IL-1β, and IL-6 play a vital role in the development of hypertension." (PMID 29573749, 2018). "Despite having higher renal expression of Nlrp3, Casp-1 and Il-1β, Ang II-induced hypertension (SBP: 139±7 mmHg) was unaffected by co-infusion of the NLRP3 inflammasome inhibitor, MCC950 (10 mg/kg/d; SBP: 145±10 mmHg)." (PMID 28659507, 2017). "AT1R inhibition has proven to reduce inflammation in hypertension, as well as LPS-induced inflammation, via the reduction of IL-1β, IL-6 and TNFα levels." (PMID 28416734, 2017). "In summary, our study suggests that TXA2 plays an important role in hypertension development through the IL-1β signaling pathway in placenta, and also provide a potential explanation of the mechanism by which aspirin prevents high-risk PE." (PMID 26974824, 2016). "Significant differences in cytokine levels were observed according to age (CD121a), BMI (IL-1β), hypertension (IL-1β and IL-8), smoking (CD121a), and alcohol consumption (CD121a and IL-1β)." (PMID 26098632, 2015). "Overactivity of the proinflammatory cytokines such as TNF-α and IL-1β in the PVN, a critical cardiovascular and autonomic center, has been implicated in the development and the maintenance of hypertension and heart failure." (PMID 25885968, 2015).